ADA2 (adenosine deaminase 2)
Diseases named in the same sentence as ADA2 in open-access papers (continued):
Sharing a sentence is not in itself a finding about the gene and the disease.
tumor (20 papers, 2018 to 2025). "An association between the activity of ADA2 in the plasma of patients with breast cancer with a pro-tumor M2 phenotype of macrophages, as well as the activity of ADA1, and endothelial cell dysfunction or inflammatory parameters was shown." (PMID 35327609, 2022). "Especially for TNBC, the inhibition of ADA2 that can redirect tumor associated macrophages into a preferred anti-tumor M1 phenotype deserves special attention." (PMID 33916440, 2021). "ADA2 is a potent regulator of tumor associated microglia/macrophages polarization." (PMID 34054547, 2021). "PEGylated ADA2 (PEGADA2) treatment suppressed tumor progression in an enzyme activity-dependent manner, modulating immune responses." (PMID 40390144, 2025). "A recent study showed that PEGylated ADA2 injection inhibited the growth of several solid tumors (including colon and breast tumors) and lung metastasis in tumor-bearing mice models, which indicated the potential value of ADA in cancer therapy." (PMID 35663977, 2022). "Noteworthy, the activity of ADA (ADA1 and ADA2) changes during the interaction of tumor cells (triple-negative breast cancer) with lymphocytes, macrophages, and endothelial cells in vitro, providing unfavorable phenotype and contributing to cancer progression." (PMID 35327609, 2022). "Human Protein Atlas (HPA) and Gene Expression Profiling Interactive Analysis (GEPIA2) databases were used to analyze the mRNA expression of ADA1 and ADA2 in human normal cells and tumor tissues." (PMID 35663977, 2022). "Adenosine deaminase 2 (CECR1) is highly expressed by TAMs, contributing to tumor angiogenesis." (PMID 38580870, 2024). "Furthermore, we investigated the differential expression of ADA1 and ADA2 between tumor and normal tissues." (PMID 35663977, 2022). "It was proposed that PEGylated ADA2 could inhibit tumor growth by decreasing the extracellular concentration of adenosine." (PMID 35967411, 2022). "This may be especially important for tumor progression, as ADA2, on the one hand, effectively degrades adenosine in a hypoxic tumor microenvironment, but also acts as a growth factor for anti-inflammatory M2 macrophages." (PMID 33916440, 2021). "Especially in TNBC, the inhibition of ADA2 that can redirect macrophages into the preferred anti-tumor M1 phenotype deserves attention, while the suppression of ADA1 activity may be of importance to protect the endothelium and reduce metastasis." (PMID 33916440, 2021). "Thus, as the enzymes that catalyze adenosine degradation, ADA1 and ADA2 may play important roles during tumor development." (PMID 35663977, 2022). "Additionally, the changes in ADA2 activity that may contribute to the differentiation of macrophages into unfavorable pro-tumor M2 phenotype deserve special attention in TNBC." (PMID 33916440, 2021). "Therefore, ADA2 is expected to act as a biomarker to regulate tumor immune response." (PMID 34654352, 2021). "To explore whether ADA was involved in the process of tumor-immune infiltration, we employed TIMER2.0 to analyze the correlation between tumor-infiltrating immune cells and the expression of ADA1 and ADA2." (PMID 35663977, 2022). "Notably, in LAML, OV, and PAAD tumor tissues, both ADA1 and ADA2 were increased, while in STAD tumor tissues, the expression changes of ADA1 and ADA2 were opposite." (PMID 35663977, 2022). "Notably, the ADA1 and ADA2 levels in tumor tissues and serum from cancer patients do not have a corresponding relationship." (PMID 35663977, 2022).
cancer (17 papers, 2015 to 2025). A tumor composed of atypical neoplastic, often pleomorphic cells that invade other tissues. "It was recently found that ADA2 is a prognostic factor associated with prolonged cancer patient survival." (PMID 35967411, 2022). "Thus, we further screened the ADA1 and ADA2 expression-associated genes in these cancers and performed a functional analysis of these genes." (PMID 35663977, 2022). "In general, the mutation frequency of ADA1 and ADA2 in cancers was low." (PMID 35663977, 2022). "In cancers with a significant association with ADA1 or ADA2 levels, higher ADA1 showed a poor prognosis (except for THYM), while higher ADA2 was associated with better survival." (PMID 35663977, 2022). "Another study has shown that the decrease in ADA2 activity in serum of patients with breast, gastric, colon cancer, and lymphoma, in particular, correlates with the effectiveness of the cancer treatment." (PMID 35967411, 2022). "Multiple clinical studies have shown that the activity of ADA2 increases in response to intracellular pathogens and cancers." (PMID 35967411, 2022). "Taken together, these results demonstrated the different prognostic value between ADA1 and ADA2 in several types of cancers." (PMID 35663977, 2022). "The area below the ROC curve was above 0.8 and 0.85, respectively, indicating that ADA2 is a good predictive marker for the studied types of cancer." (PMID 35967411, 2022). "The concentration of ADA2 in serum is increased in several inflammatory disorders and cancers, especially blood cancers." (PMID 35967411, 2022). "In conclusion, we applied integrated bioinformatics analysis to demonstrate the roles of ADA1 and ADA2 in cancers." (PMID 35663977, 2022). "Deep deletion of ADA1 was rare in most cancers, while deep deletion of ADA2 was found in most cancers." (PMID 35663977, 2022). "Here, we conducted a pan-cancer analysis to illustrate the potential function of ADA1 and ADA2 in cancers." (PMID 35663977, 2022). "Recently, PEGylated ADA2 (PEGADA2) was studied on preclinical cancer models, providing promising results for clinical application." (PMID 35327609, 2022). "The highlighted results of this study are as follows: firstly, the ADA1 and ADA2 showed opposite prognostic values in several types of cancers." (PMID 35663977, 2022). "Based on the analysis of this study, the potential antitumor effects of ADA2 proteins or ADA2 agonists in more cancers needed to be investigated." (PMID 35663977, 2022). "The increase in ADA2 concentration was significantly higher in all patients with cancer, patients undergoing treatment, and untreated patients." (PMID 35967411, 2022). "These include: CDH1, MUC1, THBS4, and MSLN for PEs related to cancer; ADA2, CXCL10, and WARS for TB-PEs; CRP, S100A9, and VIM for parapneumonic PEs; and C9, LDHA, HPX, LDHB, and C3 for benign-PEs." (PMID 35197508, 2022). "To demonstrate that ADA2 can be used as a predictive marker for active cancer, we constructed a ROC curve for ADA2 concentration in the samples from all cancer patients and the patients on treatment." (PMID 35967411, 2022). "We concluded that ADA1 was a poor prognostic marker in several cancers, while ADA2 was a favorable prognostic marker." (PMID 35663977, 2022). "THP-1 cells revealed increased activities of both, ecto-tADA, and ecto-ADA2 after incubation with cancer cell media." (PMID 33916440, 2021). "Ecto-ADA2 activity particularly increased on the surface of THP-1 cells in a co-culture with cancer cells using 8 μm size pore inserts." (PMID 33916440, 2021). "On the other hand, the treatment of immune and endothelial cells with cancer cell medium, increased ecto-ADA2 activity on THP-1 monocytes/macrophages and ecto-ADA1 on Jurkat and HULEC." (PMID 33916440, 2021).
cancer (continued). "While our studies on the antitumour potential of ADA activity inhibition have been performed in mice that lack ADA2, which plays a key role in the abolishment of immune surveillance leading to cancer progression, dCF is known to affects both ADA isoenzymes." (PMID 30291675, 2018). "ADA2 may serve as a novel target for antiangiogenic therapy in some types of human cancer, which could ultimately provide individuals suffering from this terrible affliction with the best possible care." (PMID 36606112, 2023). "NKG7 is the only gene that positively related to both ADA1 and ADA2 in three cancers." (PMID 35663977, 2022). "Moreover, by using clinical samples, we investigated the change of serum ADA1 and ADA2 activities in various cancers." (PMID 35663977, 2022). "The relationship between ADA2 and infiltrating immune cells was consistent across pan-cancer." (PMID 35663977, 2022). "The enzyme assay was used to detect the ADA1 and ADA2 activities in serum from cancer patients." (PMID 35663977, 2022). "As a secretory protein, ADA2 was increased in serum in most cancers." (PMID 35663977, 2022). "However, serum ADA2 activities were significantly increased in most cancers, except in READ, STAD, and THCA." (PMID 35663977, 2022). "Taken together, because of these differences between ADA1 and ADA2, we presume that ADA1 and ADA2 may play different roles in cancers." (PMID 35663977, 2022). "In this study, we investigated the distinct roles of ADA1 and ADA2 in pan-cancer." (PMID 35663977, 2022). "This study aims to explore the roles of ADA1 and ADA2 in cancers." (PMID 35663977, 2022). "Nevertheless, our results suggest that high ADA2 concentration in saliva could indicate persistent activation of the immune system in response to cancer." (PMID 35967411, 2022). "Surprisingly, we found many cancer patients with increased ADA2 concentration in saliva." (PMID 35967411, 2022). "Thus, although the ADA isoenzymes ADA1 and ADA2 play different roles in cancer development, the functions and mechanisms for ADA1 and ADA2 need to be validated by further studies." (PMID 35663977, 2022). "This will ultimately not only aid in optimizing the treatment of patients suffering from this devastating condition, but ADA2 might also be a new target for antiangiogenic therapy in certain types of human cancer." (PMID 29951947, 2018). "Thus, ADA2, as a marker, could be helpful in follow-up the treatment of cancer patients where ADA2 concentration is significantly elevated." (PMID 35967411, 2022). "Furthermore, for ADA2 alteration, the top 5 cancers were UCEC, SKCM, STAD, ESCA, and LUSC." (PMID 35663977, 2022). "Moreover, ADA1/ADA2 ratio grew with cancer stage in HR+HER2+ BC." (PMID 33916440, 2021). "However, they caused an increase in the ADA1 activity, and did not alter ADA2 activity in cancer cells." (PMID 33916440, 2021). "Secondly, in the different correlation profiles between infiltrating immune cells and ADA1 or ADA2, ADA1 showed a moderate positive correlation with multiple infiltrating immune cells in most cancers except THYM." (PMID 35663977, 2022). "A similar pattern of plasma ADA iso-enzyme activities was maintained in HR+HER2- BC according to the rate of cancer development, but only a tendency in increased ADA1 activity and ADA1/ADA2 ratio was observed." (PMID 33916440, 2021). "Nonetheless, the ADA2 assay offers a significant advance in TB diagnostics, providing enhanced specificity, a streamlined workflow, and adaptability to other ADA2-related conditions, such as DADA2, HIV, and cancer." (PMID 40895545, 2025). "However, the studies about ADA in cancers are still few, and the roles of ADA1 and ADA2 in pan-cancer are still unclear." (PMID 35663977, 2022). "At the same time, ADA2 could be used as an additional marker to confirm LGLL and follow up on the treatment of this cancer." (PMID 35967411, 2022).
cancer (continued). "There were no significant changes in serum ADA1 activities in most cancers, while serum ADA2 activities were increased in most cancers." (PMID 35663977, 2022). "Significant alterations in both ADA iso-enzyme activities (ADA1 and ADA2) have been found as a result of TNBC cell interactions with macrophages, lymphocytes, and endothelial cells in vitro providing an unfavorable phenotype related to cancer progression." (PMID 33916440, 2021). "In each type of cancer cells co-culture with Jurkat cells, ecto-tADA activity was increased, while ecto-ADA2 was not changed." (PMID 33916440, 2021). "The use of ADA2 as a marker of immune disorders and cancer in saliva has not been fully explored." (PMID 35967411, 2022). "We have shown that ecto-tADA activity was increased on MDA-MB-231 cancer cells after the incubation with medium obtained from immune (THP-1 and Jurkat) and endothelial (HULEC) cells, while their effect on ecto-ADA2 activity was not changed." (PMID 33916440, 2021). "However, the function and clinical value of ADA in cancers have not been well analyzed, including ADA1 and ADA2." (PMID 35663977, 2022).
genetic disorder (4 papers, 2015 to 2025). "Deficiency of ADA2 (DADA2) is a rare genetic disorder caused by a biallelic mutation of the ADA2 gene." (PMID 40181996, 2025). "The recently described genetic disorder “deficiency of ADA2” is being considered in both sisters, but yet unproven." (PMID 26590091, 2015).
hematological disease (3 papers, 2021 to 2022). "Mutations with a complete lack of ADA2 protein in such a transfection system are more likely to present with hematological disease." (PMID 35095905, 2021).
respiratory diseases (2 papers, 2017 to 2022). "We also checked whether inflammation or respiratory diseases affect the concentration of ADA2 in saliva." (PMID 35967411, 2022). "Moreover, the levels of ADA2 activity observed in animals suffering from gastrointestinal and respiratory disorders were statistically significantly higher than those reported in healthy animals." (PMID 28594948, 2017).
bacterial infection (1 paper, 2025). "Indeed, ADA2 protein expression is upregulated by viral and bacterial infection in vitro and in vivo (EBV, SARS-CoV-2, HTLV-1 and HIV, Mycobacterium tuberculosis)." (PMID 40864493, 2025).
metabolic disease (1 paper, 2021). A congenital disorder (due to inherited enzyme abnormality) or acquired (due to failure of a metabolically important organ) disorder resulting from an abnormal metabolic process. "Fourth, ADA has two isoenzymes ADA1 and ADA2, which may paly different roles in T2D and other metabolic disease." (PMID 34001220, 2021).
ADA2 also shares sentences with these, for which no sentence is quoted: familial Mediterranean fever (6 papers); Blau syndrome (4); Livedo reticularis (4); Aicardi-Goutières syndrome (3); Arthritis (3); autoimmune lymphoproliferative syndrome (3); triple-negative breast carcinoma (3); Behçet’s disease (2); cryopyrin-associated periodic syndrome (2); diffuse large B-cell lymphoma (2); Griscelli syndrome (2); infectious disease (2); intracranial hemorrhage (2); pulmonary TB (2); pure red-cell aplasia (2); Sneddon syndrome (2); systemic juvenile idiopathic arthritis (2); Thrombocytopenia (2); viral diseases (2); acquired immunodeficiency syndrome (1); acute myeloid leukemia (1); acute respiratory distress syndrome (1); adenoma (1); aplastic anemia (1); asthma (1); atherosclerosis (1); autoimmune liver disease (1); autoimmune polyendocrinopathy (1); autosomal recessive disease (1); B-cell lymphoma (1).
A further 84 diseases each share a sentence with ADA2 in 1 paper.